EGFR (epidermal growth factor receptor)
Diseases named in the same sentence as EGFR in open-access papers (continued):
Sharing a sentence is not in itself a finding about the gene and the disease.
tumor (continued). "Tumours expressing both EGFR and phospho-EGFR had similar survival as EGFR alone." (PMID 19997103, 2010). "We then determined whether tumours expressing both EGFR and phospho-EGFR (n=158) had a poorer prognosis compared with those with EGFR alone." (PMID 19997103, 2010). "Patients with refractory, EGFR-undetectable mCRC who had undergone at least one standard chemotherapy regimen containing fluoropyrimidine were given cetuximab in the standard dosage regimen and evaluated for tumor response every six weeks." (PMID 20680105, 2010). "A preclinical study of subcutaneously transplanted human lung cancer cells supports this hypothesis, as TGF-α mediates tumor sensitivity to EGFR inhibitors in this system." (PMID 20975924, 2010). "The EGFR protein expression was positive in 34 tumours (79%)." (PMID 20664595, 2010). "Although EGFR and Her-2 are frequently overexpressed in OSCC, few studies evaluated these proteins in saliva and their association with the tumor, which may represent potential usefulness in a clinical setting." (PMID 20429940, 2010). "Furthermore, in the same study the EGFR-targeted vector significantly delayed tumor growth in a murine xenograft model." (PMID 21994621, 2010). "Furthermore, tumours with strong (3+) EGFR staining intensity (vs other) had a higher mean and median number of Ki-67-positive tumour cells (n=361; P=0.0002)." (PMID 19997103, 2010). "Patients with these tumours who require oncological treatment in addition to surgery could benefit from EGFR and mitogen-activated protein kinase pathway inhibitors." (PMID 20664595, 2010). "Therefore, since plasma samples of patients with NSCLC often contain circulating DNA derived from tumor tissues, plasma samples have been used for detecting genetic alterations, in particular for EGFR." (PMID 21532835, 2010). "From February 2004 to May 2007 101 CRC patients (62 male, 39 females; median age 63 years, range 26-80) were screened for EGFR tumor expression and treated with Cetuximab." (PMID 20398370, 2010). "The expression of EGFR mRNA in tumor tissue was positively correlated with EGFR protein in plasma." (PMID 21159244, 2010). "This evidence suggests that TGFαL3SEAD227A also affects EGFR-expressing mouse tumours." (PMID 21176167, 2010). "Congruent with this hypothesis, tumors treated with an EGFR inhibitor displayed a significant ~27% decrease in mature pericyte coverage of the tumor endothelium." (PMID 20975924, 2010). "In tumor cell lines, gefitinib inhibits the growth of cells that express high levels of EGFR." (PMID 21050422, 2010). "High-EGFR protein expression was associated with high-histological grade of tumour (P<0.001, ANOVA), but it was associated with neither disease-free interval (P=0.286) nor overall survival (P=0.307)." (PMID 20664595, 2010). "In addition to the 3 amplicons containing the EGFR locus, two other amplicons were present in tumour." (PMID 21170331, 2010). "Moreover, EGFR expression correlates with tumor resistance to chemotherapy and indicates a poor prognosis." (PMID 20509930, 2010). "The EGFR is thought to play an important role in the regulation of cell division and tumor growth." (PMID 20509969, 2010). "Similarly, GAs suppress EGFR/HER2 signaling, impair multiple pathways associated with receptor upregulation, and reduce tumor growth and vascularization in vivo." (PMID 20628489, 2010).
tumor (continued). "Moreover, the predictive role of EGFR expression on tumour response and locoregional recurrence has been extensively investigated in patients with LARC treated with preoperative chemoradiation therapy." (PMID 20842128, 2010). "Weak/moderate (1+ and 2+) staining intensity (vs absent) for phospho-EGFR was associated with a higher mean and median number of Ki-67-positive tumour cells (P=0.015)." (PMID 19997103, 2010). "In addition, some studies showed a strong correlation between EGFR positivity and high grade, late stage, tumor progression and poor clinical outcome in the classic TCC of the bladder." (PMID 19171060, 2009). "In addition, VEGF upregulation in tumour cells is considered to be a mechanism of resistance to EGFR inhibitors." (PMID 19319137, 2009). "However, multivariate analysis showed that only high EGFR overexpression, metastatic recurrence, high tumor grade and the combination of ≥ 2 affected markers were independent prognostic factors." (PMID 19171060, 2009). "Importantly, epithelial tumor cells including SCCHN that have undergone EMT and acquired mesenchymal characteristics are more resistant to EGFR-targeted therapies than tumor cells that have epithelial characteristics." (PMID 19636423, 2009). "Thus, dEGFRλ;dp110CAAX induces neoplasia via coordinated stimulation of G1-S entry through dCyclinE, and G2-M progression through Stg, both of which are EGFR-Ras dependent outputs." (PMID 19214224, 2009). "Interestingly, analysis of tumour samples from the tribute study demonstrated a lower response rate among patients whose tumours demonstrated EGFR amplification." (PMID 19229369, 2009). "Activated EGFR triggers diverse signalling pathways in tumour cells." (PMID 19088723, 2009). "The range of reported prevalence of EGFR gene amplification may be due to differences in expression by tumor anatomical site." (PMID 19636423, 2009). "Head and neck tumors have a high rate of EGFR overexpression, which may suggest that these tumors as a class are more EGFR-dependent than other tumor types." (PMID 19657384, 2009). "Improvement in blood flow leading to better drug delivery or increased tumor oxygenation offers a rationale as to why these EGFR inhibitors might perhaps be started prior to cytotoxic therapy and continued through this therapy." (PMID 19657384, 2009). "Similarly, we found a significant increase in the rate of HER2 gene amplification from grade 1 to 3 tumours, and conversely a significant decrease in the rate of EGFR expression from grade 1 to 3 tumours (P=0.028 and P=0.016, respectively)." (PMID 19088718, 2009). "LL2-tumor bearing C57B6 mice were immunized four times at weekly intervals with EGFR DNA vaccine." (PMID 19178753, 2009). "In their analysis, triple negative, CK5/6-positive and EGFR-positive tumours were selected." (PMID 19695088, 2009). "Taken together, it was found that these tumor suppressor/susceptibility genes can regulate key molecules involved in cell signal pathways such as ras/MEK/ERK, Rb/E2F and EGFR ras/MEK/MAPK, and can regulate the expression of some adhesion molecules such as ezrin, nm23 and α-catenin." (PMID 19949542, 2009). "Analysis of tumour samples from ideal 1 and 2 showed no significant improvement in ttp or survival for patients with EGFR mutations or with EGFR amplification." (PMID 19229369, 2009). "Despite more investigation is needed, these evidences suggest that the blockade of the EGFR by specific mAbs may antagonise the role of the TGF-β on promote tumour cell invasion and metastasis after a radiation therapy." (PMID 19293809, 2009). "The following biomarkers had results available in 95–100% of tumour samples: EGFR; HER2; ER; PgR." (PMID 19844234, 2009). "Upregulated EGFR signaling is known to initiate a cascade of events leading to cell proliferation, migration, invasion and blocking of apoptosis that eventually leads to tumor progression." (PMID 19878607, 2009).
tumor (continued). "Our studies show that targeting tumor cells with EGFR inhibitors may modulate the TME via vascular normalization to increase response to chemotherapy and radiotherapy." (PMID 19657384, 2009). "Because integrin clusters are known to recruit other molecules to membrane complexes, we hypothesized that α6β4 clustering might lead to the redistribution and clustering of EGFR on the tumor cell surface." (PMID 19470173, 2009). "The concept that primary tumour and distant metastasis may indeed show different molecular patterns is supported by the assessment of EGFR gene status by FISH." (PMID 19293803, 2009). "At day 5, when the tumor was palpable, we immunized the mice with Sec-N'-EGFR DNA vaccine four times at weekly intervals via three different methods: intramuscular injection (i.m), gene gun administration of gold-coated DNA, and gene gun administration of non-coating DNA." (PMID 19178753, 2009). "We hypothesize that this integrin-EGFR crosstalk may facilitate tumor cell cytoskeletal rearrangements important for tumor progression." (PMID 19470173, 2009). "Therefore, the anti-tumour effect of vandetanib in this model appears to be mediated by inhibiting tumour angiogenesis (anti-VEGFR effect) as well as by directly inhibiting tumour cell proliferation (anti-EGFR effect)." (PMID 19319137, 2009). "Remarkably, none of the five new K-Ras mutated patients with more than 50% of tumour cells, presented an EGFR mutation (exon 18, 19, 20, 21) (data not shown)." (PMID 19293811, 2009). "To see whether improvements in tumor vascular function through targeting EGFR achieved comparable effects as anti-VEGF therapy in our model, we treated mice with SQ20B xenografts with the anti-VEFR monoclonal antibody bevacizumab." (PMID 19657384, 2009). "Interestingly, all of the patients (N=11) having EGFR tumour expression detected by immunohistochemistry together with low levels of both serum EGF (<667 pg ml−1) and TGF-α (<14 pg ml−1) showed a response." (PMID 19127259, 2009). "More importantly, the administration of high light dose for this experiment was to test our hypothesis that combining PDT with Erbitux can improve tumor control and also to evaluate the effectiveness of Erbitux in reducing EGFR concentrations." (PMID 19878607, 2009). "Our simulation results suggest that extra sensitivity in the downstream regions of the EGFR signaling pathway may be exploited for the purpose of inhibiting EGFR signaling in tumour cells." (PMID 20028552, 2009). "Accordingly, we determined the expression levels of the activated receptor (pEGFR), and the activated cytosolic end points to the three branches of the EGFR pathway (pAkt, pStat3 and pErk1/2) in pre-treatment samples of tumor tissue from patients undergoing TKI therapy and response assessment." (PMID 19765296, 2009). "In addition, such studies have correlated the overexpression of the EGFR with radioresistance, whereas the EGFR blockade increases the sensitivity of tumour cells to radiation therapy." (PMID 19293809, 2009). "It is possible that some of the features of the PDGF signaling pattern are influenced by prior treatment though it is unlikely that this accounts for the genotypic differences in this proteomic tumor class, such as the paucity of EGFR amplification, chr7 gain and Ink4a/ARF locus deletion." (PMID 19915670, 2009). "On multivariate analysis, only increased EGFR expression (protein or RNA), the presence of metastasis and/or recurrence, a high tumor grade (GII &GIII) and a combination of aberrant markers (≥ 2) were significantly associated with reduced OS rates (p = 0.022&0.025, p = 0.000, p = 0.001, p = 0.001)." (PMID 19171060, 2009). "In the one discordant case, further analyses revealed that a tumor mosaicism or multiple primary tumors were present, indicating that anti-EGFR therapy has no influence on KRAS/BRAF mutation status in mCRC." (PMID 20300583, 2009).
tumor (continued). "Based on the results of experimental models, an exploratory analysis of the relation between BRCA1, RAP 80 and Abraxas mRNA expression was performed in 86 of 111 patients without EGFR mutations for whom sufficient tumor tissue was available." (PMID 19415121, 2009). "Interestingly, we found stronger EGFR staining was present at the leading edge of tumor invasion in high-grade tumors of luminal B subtype." (PMID 19442295, 2009). "This integrin-mediated selective augmentation of EGFR signaling might promote tumor cell cytoskeletal rearrangements important for tumor progression." (PMID 19470173, 2009). "The first group should not be addressed to anti-EGFR MoAb treatments based on the sole primary tumour evaluation, but eventually, it may benefit from these targeted therapies because of the presence of EGFR gene CNG in metastatic sites." (PMID 19293803, 2009). "Our results offer insight into how targeting tumor cells with EGFR inhibitors may modulate the TME to improve sensitivity to chemotherapy or radiotherapy." (PMID 19657384, 2009). "They appear to work, in part, by inhibiting the effects of gain-of-function mutations in EGFR, but patients with tumours lacking mutations benefit as well." (PMID 19240716, 2009). "However, vandetanib also inhibited tumour growth even in the OZ (refractory to EGFR inhibition) xenograft, when given at higher dose." (PMID 19319137, 2009). "In seven cases with a different EGFR gene status pattern between primary tumour and distant metastasis and for which a lymph node metastasis was available, the EGFR gene status in the lymph node lesion was similar to that in primary tumour in five cases and to distant metastasis in two cases." (PMID 19293803, 2009). "More relevant endpoints in EGFR-/Src-targeted trials than tumor shrinkage may include time to progression or overall survival." (PMID 19636423, 2009). "We hypothesize that α6β4 integrin clustering at the leading edge of a tumor might lead to a redistribution and concentration of EGFR at the invading front, thereby promoting the motility of tumor cells towards an EGF gradient." (PMID 19470173, 2009). "Hypothesizing that this might normalize tumor vasculature, we examined the effects of the EGFR inhibitor erlotinib on tumor vascular function, tumor microenvironment (TME) and chemotherapy and radiotherapy sensitivity." (PMID 19657384, 2009). "Whereas only 10% of the baseline tumor cell population fell within the region on the bivariate dot plot to the left of the diagonal, representing cells with clustered EGFR above an arbitrarily defined threshold, the proportion increased to 65% after crosslinking α6β4 integrin." (PMID 19470173, 2009). "It has been shown that activated EGFR strongly correlate with tumor invasion and metastasis in EC." (PMID 19917135, 2009). "Results from several other studies have suggested that inhibition of the VEGF and EGFR pathways may have activity in other tumor types." (PMID 20016807, 2009). "All tumour samples showed a positive EGFR expression as detected by IHC." (PMID 19293803, 2009). "After homing to the lung vasculature, therefore, tumor cells with EGFR clustering might undergo an augmented response to EGF, favoring directed motility towards EGF in the adjacent lung tissue." (PMID 19470173, 2009). "The EGFR signalling pathway is associated with the progression, proliferation, migration, and survival of cancer cells, and VEGF plays a key role in tumour-associated neo-angiogenesis, which provides a tumour with oxygen, nutrition, and a route for metastasis." (PMID 19319137, 2009). "A positive EGFR immunostaining was detected in all analysed tumour samples." (PMID 19293809, 2009). "As α6β4 signaling through Rho promotes tumor cell motility, a selective augmentation of EGFR-mediated Rho activation might further promote tumor cell migration." (PMID 19470173, 2009).
tumor (continued). "During promotion, the majority of genes identified in the BALBLps-d compared to BALB/c mice (P < 0.05) were involved in epithelial growth factor receptor (EGFR) signaling (e.g. epiregulin (Ereg)), secreted phosphoprotein 1(Spp1)), which can lead to cell growth and eventual tumor development." (PMID 19925653, 2009). "Alternatively, circulating tumor cells might bind endothelial hCLCA2, crosslinking α6β4 and inducing EGFR clustering." (PMID 19470173, 2009). "In total, 21 patients with EGFR-positive tumours received study treatment." (PMID 19238629, 2008). "Importantly, we identified a subset of patients with cortactin-overexpressing tumours that displayed low EGFR levels and a survival rate that equalled that of patients with tumoral overexpression of both EGFR and cortactin." (PMID 18268492, 2008). "Tumours that overexpress cortactin were largely positive for EGFR." (PMID 18268492, 2008). "Secondary objectives were to explore whether the EGFR expression pattern correlated to EGFR and/or K-RAS mutations in both the primary tumours and corresponding metastases." (PMID 19238633, 2008). "Therefore, we measured EGFR and its major downstream targets in tumours to demonstrate drug-mediated effects on critical cell signalling pathways from treated mice." (PMID 18797454, 2008). "EGFR itself and its downstream signalling pathways are promising targets for anti-tumour drugs." (PMID 18380891, 2008). "It is thought that EGFR is one of the newest therapeutic targets for many tumours." (PMID 19014499, 2008). "Similarly, two other studies in paired NSCLC tumours showed a discordance of 32 and 27% regarding the EGFR gene copy number, whereas another study including six NSCLC patients of Asian ethnicity reported a 100% concordance in regard to EGFR mutation status." (PMID 19238633, 2008). "Other growth stimulatory pathways that are essential for tumor cell viability must be targeted in order to obtain a therapeutic response, may it be simultaneously with EGFR/VEGFR-2 inhibition or by other means." (PMID 18177496, 2008). "Their existence is important clinically, because these cells will be less likely to respond to drugs that target cells with elevated EGFR signalling and may be capable of reinitiating tumour growth following therapy." (PMID 18657901, 2008). "In contrast, there was a significant inverse relationship of LKB1 mutations with EGFR mutations in both NSCLC tumours and cell lines, which has not previously been described." (PMID 18594528, 2008). "The anti-EGFR monoclonal antibody cetuximab has been approved for the treatment of metastatic CRC, however tumor response to cetuximab has not been found to be associated with EGFR over-expression by immunohistochemistry (IHC)." (PMID 18700047, 2008). "Tumours from bitransgenic mice overexpress the myr-Akt1 and ErbB2 transgenes, but there was dramatically less overexpression and phosphorylation of ErbB3, diminished phosphorylation of ErbB2, decreased level of EGFR protein and undetectable ErbB4 protein." (PMID 18700973, 2008). "In a retrospective analysis, examining GBM tumours from patients treated with signal transduction inhibitors, such as the EGFR TKIs erlotinib or gefitinib, clinical response was highly correlated with co-expression of tumour suppressor PTEN and EGFRvIII in 10%–20% of patients." (PMID 22275966, 2008). "Én 19 patients sufficient tumour tissue was available for immunohistochemical analysis of EGFR." (PMID 19238633, 2008). "A study on a larger series of matched histological and cytological specimens is under way to investigate the impact of tumour heterogeneity and cell count on the EGFR FISH status, and to define better criteria of a positive EGFR FISH result in cytological specimens." (PMID 18087280, 2008). "Like EGFR, Id-1 has been shown to have an up-regulation in many tumours." (PMID 19014499, 2008).